IRS1 (insulin receptor substrate 1)
Diseases named in the same sentence as IRS1 in open-access papers (continued):
Sharing a sentence is not in itself a finding about the gene and the disease.
Hypertension (17 papers, 2009 to 2025). The presence of chronic increased pressure in the systemic arterial system. "IR has been recognized as an independent risk factor of hypertension, and insulin mediated-activation of endothelial IRS-1/PI3K/AKT/eNOS pathway is unique biological action for regulating vasodilation and arterial pressure." (PMID 33841146, 2021). "In the PT, IRS2-mediated pathway is preserved and the stimulation of sodium reabsorption by insulin causes sodium retention and possibly subsequent hypertension, whereas the potential impairment of the IRS1-mediated pathway could lead to unsuppressed gluconeogenesis." (PMID 27247938, 2016). "The major findings of the present study are: sunitinib administration led to an impairment of vascular function and hypertension in rats, via IRS-1- and Pellino-1-mediated inhibition of AKT/eNOS signaling and reduction of NO production." (PMID 33841146, 2021). "Our results demonstrated the potential molecular mechanisms by which sunitinib causes endothelium-dependent vasodilation dysfunction and hypertension, where we demonstrated the upstream signaling of AKT/eNOS/NO appears to be IRS-1." (PMID 33841146, 2021). "Among participants without dementia, a significant positive relationship was detected between hypertension and IKKβ, IRS1 and JNK." (PMID 27106634, 2017). "Pathological stimuli-induced attenuation of endothelial IRS-1/PI3K/AKT/eNOS activation is an important molecular mechanism of endothelial damage, which promotes the incidence of hypertension." (PMID 33841146, 2021). "Our search revealed both known KDs showing connections to hypertension or relevant conditions in one or more types of studies (99 KDs; such as GNAS, SLC2A3, IRS1, ADM, and SERPINE1) and relatively novel KDs in BP studies (such as SPTBN1 and GNB1)." (PMID 30931314, 2019). "Instead, novel correlations between IGF1R, IRS1, IRS2, and insulin appeared with hypertension demonstrating that IGF1 is no longer responsible for activation of intracellular processes through IGF1R." (PMID 31327319, 2019). "In hypertension, IGF1 was no longer responsible for intracellular activation and lost its correlation to IRS1/2 adaptor proteins." (PMID 31327319, 2019).
glioma (15 papers, 2010 to 2024). A benign or malignant brain and spinal cord tumor that arises from glial cells (astrocytes, oligodendrocytes, ependymal cells). "Specifically, the upregulation of miR-126 leads to the suppression of IRS-1, which is associated with the promotion of glioma cancer stem cell formation." (PMID 39348350, 2024). "Role of JAK2 in Hormone-like Cytokine Signaling stood out because GHR (growth hormone receptor) and IRS1 (insulin receptor substrate 1) has been linked with glioma progression." (PMID 27669421, 2016). "This regulatory relationship between miR-126 and IRS-1 has significant implications for the behavior of glioma cells." (PMID 39348350, 2024). "In an effort to restore viral synthesis in glioma cells, the IRS1 gene from human cytomegalovirus (HCMV) was introduced into the genome." (PMID 33535555, 2021). "Taken together, we concluded that miR-126 enhances the formation of glioma cancer stem cell probablyvia down regulation of IRS-1 in neurotrophin signaling pathway." (PMID 29633591, 2018). "Our results demonstrated that overexpression of miR‐497 is significantly correlated with TMZ resistance in glioma cells by regulating the IGF1R/IRS1 pathway." (PMID 28064447, 2017). "Studies also suggest that this inverse regulation of miR-126 and IRS-1 could trigger glioma cancer stem cell formation." (PMID 39348350, 2024). "Furthermore, miR-128-3p was demonstrated to inhibit glioma cell proliferation and differentiation through the IRS-1/PI3K/AKT signaling pathway." (PMID 32178675, 2020). "Furthermore, experiments conducted in insulin-stimulated IRS-1-transfected glioma cell showed high phosphorylation levels of AKT, ERK1/2 and overexpression of Grb2 resulting in increased cell viability." (PMID 33604294, 2020). "The increased level of miR‐497 in TMZ‐resistant glioma cells was concurrent with the up‐regulation of insulin‐like growth factor 1 receptor (IGF1R)/insulin receptor substrate 1 (IRS1) pathway‐related proteins, that is, IGF1R, IRS1, mammalian target of rapamycin (mTOR), and Bcl‐2." (PMID 28064447, 2017). "We hypothesized that miR‐497 could regulate TMZ resistance in glioma cells by targeting IGF1R/IRS1 pathway." (PMID 28064447, 2017). "Our results demonstrated that the down‐regulation of miR‐497 could inhibit the levels of IGF1R/IRS1 signal pathway‐related proteins in TMZ‐resistant glioma cells both in vitro and in vivo." (PMID 28064447, 2017). "However, the association of miR‐497 and chemosensitivity of IGF1R/IRS1 pathway has not yet been explored in glioma." (PMID 28064447, 2017). "In glioma, the level of miR-128-3p expression was dramatically attenuated in glioma clinical tissues, and miR-128-3p regulated the progression of glioma via targeting NPTX1 and activating the IRS-1/PI3K/AKT signaling pathway." (PMID 32377170, 2020). "Our result revealed that the protein levels of IGF1R, IRS1, mTOR, and Bcl‐2 were increased in TMZ‐resistant glioma cells (U87‐TR and SF295‐TR) compared with TMZ‐sensitive glioma cells (U87 and SF295)." (PMID 28064447, 2017). "The IRS1 gene product improves this virus’s oncolytic effect in glioma cells by allowing for late viral synthesis and does not restore wild-type neurovirulence in noncancerous cells." (PMID 33535555, 2021). "We demonstrated that miR‐497 could regulate TMZ resistance in glioma cells by promoting cell proliferation and inhibiting apoptosis, at least partially, via targeting the IGF1R/IRS1 pathway." (PMID 28064447, 2017). "In conclusion, our results are consistent with the hypothesis that miR‐497 as a glioma promoter, is significantly correlated with the TMZ resistance of human glioma cells by targeting the IGF1R/IRS1 pathway both in vitro and in vivo." (PMID 28064447, 2017).
glioma (continued). "In other cancer types, including glioma and HCC, LBX2-AS1 affects cell proliferation and apoptosis through the miR-491-5p-leukemia inhibitory factor (LIF)-signal transducer and activator of transcription 3 (STAT3) and miR-384-insulin receptor substrate 1 (IRS1) pathways, respectively." (PMID 36131071, 2023).
heart failure (15 papers, 2011 to 2025). Inability of the heart to pump blood at an adequate rate to meet tissue metabolic requirements. "These genes included IRS1 encoding insulin receptor substrate, the major component of insulin signaling, the loss of which leads to heart failure, as well as ADCY8 encoding cAMP producing adenylate cyclase 8, which protects against cardiac stress." (PMID 37110207, 2023). "As the predicted targets of mmu-miR-696, Irs1 is reported to cause heart failure in heart-specific IRS1/IRS2 double-knockout mice." (PMID 29147650, 2017). "We therefore tested the hypothesis that loss of IR/IGF1R and IRS1/2 signaling in adult hearts would impair mitochondrial oxidative capacity to precipitate heart failure in iCIR2KO and iCIRS12KO hearts." (PMID 36125265, 2022). "Together, these data indicate that combined loss of IR/IGF1R or IRS1/IRS2 signaling in the adult heart results in impaired insulin-mediated signaling, heart failure, and increased mortality." (PMID 36125265, 2022). "Thus, distinct mechanisms mediated by IR/IGF1R and IRS1/2 contribute to heart failure following embryonic deletion versus inducible deletion of these signaling proteins in the adult heart." (PMID 36125265, 2022). "They inferred that the myocardial loss of IRS1 and IRS2 caused heart failure." (PMID 35906673, 2022). "In human advanced heart failure, Akt is paradoxically activated, with the concomitant reduction of IRS-1, thus suggesting a mechanism by which chronic Akt activation may become maladaptive, in contrast to its acute activation." (PMID 21933140, 2011). "Loss of signaling through these interaction partners could potentially result in heart failure in IRS1/2-deficient hearts by mechanisms that are independent of IR/IGF1R signaling." (PMID 36125265, 2022). "Thus, in contrast to the case with mice with prenatal loss of IRS1/2, mechanisms independent of increased autophagy contribute to heart failure in iCIR2KO and iCIRS12KO hearts." (PMID 36125265, 2022). "Both heart-specific IRS1 and IRS2 double-knockout mice and liver-specific IRS1 and IRS2 double-knockout mice prove that cardiac IR promotes heart failure." (PMID 41473239, 2025). "Double-knock-out studies have shown that cardiac suppression of IRS1 and IRS2 increases apoptosis, results in cardiac dilation and heart failure in neonatal rat ventricular cardiomyocytes." (PMID 37569355, 2023). "Chronic insulin exposure and metabolic stressors in ischemic conditions activate p38 MAPK and enhance insulin receptor substrate 1/2 (IRS1/2) degradation, culminating in AKT inactivation and eventual myocyte death and heart failure." (PMID 36770716, 2023). "Earlier studies have described heart failure in mouse models following embryonic or perinatal deletion of essential proteins involved in the IR/IGF1R signaling pathway, i.e., IR/IGF1R, IRS1/2 (13, –, 15), and mTOR." (PMID 36125265, 2022). "IRS1 is also involved in the development of coronary heart diseases, whilst the TRDN gene is involved in other forms of heart failure, ventricular tachycardia, and Romano-Ward Syndrome." (PMID 33924951, 2021). "In case of dual knockout of insulin receptor substrate-1/2 (IRS-1/2), the ATP content in cardiomyocytes was reduced, cardiomyocyte contractility and function were impaired, and the incidence of fibrosis and heart failure was increased." (PMID 36091756, 2022). "Suppressing cardiac IRS-1 and IRS-2 may serve as a fundamental mechanism for induction of heart failure." (PMID 26229969, 2015). "And inhibition of cardiac IRS1 and IRS2 may be a fundamental mechanism for inducing heart failure." (PMID 33547878, 2021).
atherosclerosis (14 papers, 2012 to 2025). A disease characterized by the build-up of fatty material and calcium deposition in the arterial wall resulting in partial or complete occlusion of the arterial lumen. "Previous studies using ApoE−/− mice heterozygous for both IR and the insulin receptor substrate-1 (IRS1) protein found that the apolipoprotein-E deficiency resulted in increased atherosclerosis development." (PMID 28752048, 2017). "Defects in IRS-1 may cause vascular damage and accelerate the progression of atherosclerosis, while IRS-2 delays neointimal formation under IR." (PMID 31258478, 2019). "Six shared loci that were shared across all traits in the analysis, all with known associations with atherosclerosis (nearest genes: MAT2A, IRS1, STAG1, PVRL2, OPRL1, ARVCF)." (PMID 40313769, 2025). "In another knock-out study, IRS1 deletion resulted in accelerated atherosclerosis in Apoe−/−-knock-out mice by increasing vascular dysfunction and inflammation." (PMID 37569355, 2023). "Although miR-126-3p has many benefits on endothelial function, it can induce atherosclerosis by increasing VSMCs proliferation via insulin receptor substrate-1 (IRS-1) inhibition." (PMID 36376958, 2022). "Furthermore, decreased insulin signaling in non-hematopoietic cells, as achieved by transplantation of ApoE−/− mouse model of atherosclerosis with bone marrow cells from IRS1+/− IR+/− ApoE−/− mice, contributed to increased atherogenesis in these mice." (PMID 28752048, 2017). "Furthermore, decreased insulin signalling in nonhaematopoietic cells, as achieved by transplantation of ApoE−/− mouse model of atherosclerosis with bone marrow cells from IRS1+/− IR+/− ApoE−/− mice, contributed to increased atherogenesis in these mice." (PMID 28899902, 2017). "Moreover ApoE−/− mice with a heterozygous deletion of the IR and its downstream target, Insulin Receptor Substrate 1 (IRS1), also develop accelerated atherosclerosis, as well as mice lacking insulin receptor substrate 2 (IRS2−/−)." (PMID 28752048, 2017). "Moreover, ApoE−/− mice with a heterozygous deletion of the IR and its downstream target, IR substrate 1 (IRS1), also develop accelerated atherosclerosis, as well as the mice lacking IR substrate 2 (IRS2−/−)." (PMID 28899902, 2017).
cognitive decline (14 papers, 2014 to 2025). "Cognitive decline is associated with serine phosphorylation of IRS1 and co-localized with neurofibrillary tangles, decreasing insulin actions by changes in the PI3K signaling pathway." (PMID 36233271, 2022). "In conclusion, the increased tyrosine phosphorylation of IRS-1 enhances insulin signal transduction in modulating of neurotransmitters associated with cognitive function and alleviating cognitive decline in brain." (PMID 24481061, 2014). "Specifically, TNF-α plays a pivotal role in cognitive decline by facilitating IRS1 phosphorylation through JNK activation, thereby modulating or inhibiting the IR in hippocampal neurons." (PMID 37762479, 2023). "We are aware that Irs1-/- mice are already protected against some aspects of cognitive decline during aging in addition to having an increased brain to body ratio compared to WT mice." (PMID 29779018, 2018). "The inhibition of ASK1 induces tyrosine phosphorylation of IRS-1 and prevents the cognitive decline in the brain." (PMID 24481061, 2014). "Taken together, these findings suggest that brain insulin signaling is associated with late-life cognitive decline and that AKT1 phosphorylation may be preferentially associated with a decline in memory, whereas IRS1 phosphorylation may be preferentially associated with perceptual speed." (PMID 38029396, 2024). "A large number of studies in the last two decades suggest that central insulin resistance and cognitive decline in AD are associated with changes in the neuronal insulin/IR signal transduction cascade, insulin grow factor 1 (IGF-1) resistance and insulin receptor substrate 1 (IRS-1) dysregulation." (PMID 37445790, 2023).
Impaired glucose tolerance (14 papers, 2015 to 2025). An abnormal resistance to glucose, i.e., a reduction in the ability to maintain glucose levels in the blood stream within normal limits following oral or intravenous administration of glucose. "Concurrently targeting IRS-1 and Lunapark, a nutritionally programmed increase in miR-126-3p causes adipose tissue insulin resistance and an ER stress response, both of which may contribute to impaired glucose tolerance." (PMID 33501603, 2021). "IRS-1 knockout females are longer lived with higher circulating insulin and impaired glucose tolerance in comparison to controls." (PMID 26061745, 2015). "This can cause mitochondrial dysfunction, endoplasmic reticulum stress (ERS), or ectopic fat deposition, interfering with insulin signaling (e.g., insulin receptor substrate 1 (IRS-1) phosphorylation) and resulting in reduced glucose uptake and impaired glucose tolerance." (PMID 40809436, 2025). "Furthermore, the acute hyperuricemic mice model showed impaired glucose tolerance and insulin tolerance accompanied by increased phospho-IRS1 (Ser307) and inhibited phospho-Akt response to insulin in myocardial tissues." (PMID 26836389, 2016). "Moreover, an HF diet produced increased liver weight and accumulation of fat deposition in the liver, whereas, FRG improved impaired glucose tolerance with upregulation of IRS-1 and Glut4 protein level expression and decreased liver weight and accumulation of fat deposition in the liver." (PMID 27322312, 2016). "Lastly, impaired glucose tolerance, IR, and resistance to IGF1 can be observed in mice with defect in IRS1 gene." (PMID 39420901, 2024).
gastric cancer (12 papers, 2010 to 2024). A primary or metastatic malignant neoplasm involving the stomach. "Furthermore, IRS1 Gly972Arg variations may be associated with an increased susceptibility to develop gastric cancer 39.The important cellular adhesion factor Paxillin (PXN) is a hallmark protein in focal adhesion (FA) site." (PMID 33162799, 2020). "NCAPD3 loss can directly inhibit CCND1 and ESR1 expression to downregulate the expression of downstream targets CDK6 and IRS1 and inhibit the proliferation of gastric cancer cells." (PMID 38711992, 2024). "Here, we found that PAFAH1B3 knockdown in gastric cancer cells downregulated the levels of IRS1, Myc, HMGB1, and PTGS2, which were reported to serve as oncogenes in many types of cancers." (PMID 33732641, 2021). "Activation of the IGF1R/IRS1 pathway has also been identified to promote drug resistance of multiple malignancies, including gastric cancer." (PMID 32192494, 2020). "A variety of miRNAs, such as miR-1271, miR-143 and miR-503, have been observed to be involved in the IGF1R/IRS1 pathway-mediated DDP resistance of gastric cancer." (PMID 32192494, 2020). "A study reported that IRS1 regulates PI3K activity to inhibit gastric cancer occurrence." (PMID 38711992, 2024). "Therefore, NCAPD3 knockdown may inhibit CCND1, MYC, and ESR1 activity to downregulate CDK6 and IRS1 expression, thereby inhibiting the proliferation of gastric cancer cells." (PMID 38711992, 2024). "Our previously studies found that Klotho protein inhibited the activation of IRS-1 / PI3K / Akt / mTOR and ERK / p70s6k and downstream signaling pathways in gastric cancer and liver cancer cells, mainly through the inhibition of IGF-1R phosphorylation." (PMID 27779100, 2016). "miR-1271 regulates cisplatin resistance of human gastric cancer cell lines by targeting IGF1R, IRS1, mTOR, and BCL2." (PMID 32309578, 2016). "Klotho is a tumor suppressor in gastric cancer, which regulates IGF-1R phosphorylation and the subsequent activation of IRS-1/PI3K/Akt/mTOR signaling, tumor cell proliferation, apoptosis, and autophagy." (PMID 23432957, 2013). "Similarly, MST1R had interactions with AKT, AKT1, and MST1, while LTR interacted with IRS1, CBL, PIK3C and SHC1, none of which have been found to be associated with gastric cancer before." (PMID 37287033, 2023).
glioblastoma (12 papers, 2016 to 2024). The most malignant astrocytic tumor (WHO grade IV). "MiR-126 plays a critical role in glioblastoma by targeting and downregulating the expression of insulin receptor substrate-1 (IRS-1)." (PMID 39348350, 2024). "It has been previously demonstrated that lncRNA XIST can control the growth and glucose metabolism in glioblastoma cells via the insulin receptor substrate 1 (IRS1)/the phosphoinositide 3-kinase (PI3K)/protein kinase B(Akt) pathway." (PMID 36035993, 2022). "In one pathway, XIST participates in glioblastoma progression by enhancing glucose metabolism via sponging miR-126 and then preventing its binding to insulin receptor substrate 1 (IRS1), thus modulating the IRS1/PI3K/Akt pathway." (PMID 35054794, 2022). "It is critical to note that the inhibition of IRS1 and IRS2 can have repressive effects on malignant behaviors observed in ovarian cancers and glioblastoma cell proliferation." (PMID 38272982, 2024). "It has been shown that reduced expression levels of miRNA-7 correlates with high levels of EGFR and upstream genes involved in Akt pathway (such as IRS-1 and IRS-2), leading to inhibition of migration, invasion and proliferation of glioblastoma cells." (PMID 32592373, 2020). "For instance, the glioblastoma resistance to receptor tyrosine kinase (RTK) inhibitors has been found to involve both genetic and epigenetic mechanisms, resulting in subclones with a gain of copy number in the insulin receptor substrate-1(IRS1) and substrate-2 (IRS2) loci." (PMID 38239396, 2023). "Finally, in glioblastoma, the lncRNA XIST was revealed to regulate glucose metabolism by targeting GLUT1 and GLUT3 through the miR-126-dependent insulin receptor substrate 1 (IRS1)/PI3K/Akt pathway and to positively control glioblastoma cell growth in vivo and in vitro." (PMID 32765426, 2020).